BMAL1 (basic helix-loop-helix ARNT like 1)
Diseases named in the same sentence as BMAL1 in open-access papers (continued):
Sharing a sentence is not in itself a finding about the gene and the disease.
Insulin resistance (37 papers, 2014 to 2026). Increased resistance towards insulin, that is, diminished effectiveness of insulin in reducing blood glucose levels. "Genome-wide association studies (GWAS) reveal that variants in BMAL1 are associated with insulin resistance, cardiovascular health, prostate cancer, lung cancer, chronotype, sociability, and neurodegeneration." (PMID 40720646, 2025). "Some scholars have found that specific knockout of BMAL1 gene in mouse liver can cause fatty liver and insulin resistance." (PMID 36976188, 2023). "Similarly, thiazolidinedione resolves the disruption of the expression of circadian clock-associated genes(Bmal1, Per2, Cry1), improving insulin resistance." (PMID 39165284, 2024). "Therefore we used this cell line to explore the mechanism of association between BMAL1 and insulin resistance in adipose tissues." (PMID 32334629, 2020). "Additionally, the expression levels of PER1, PER3, and BMAL1 molecular-clock genes in leukocytes obtained from patients with T2D was seen inversely correlated with hemoglobin A1C (HbA1c) levels, indicating an association between insulin resistance and T2D." (PMID 37475884, 2023). "In adult muscle-specific Bmal1 KOs, insulin resistance develops in part due to GLUT4 downregulation, which impairs glucose uptake." (PMID 41522721, 2026). "Disruption of WAT clocks—via high-fat diet or genetic ablation of BMAL1 or CLOCK—leads to impaired adipogenesis, altered hormone secretion, and increased risk of obesity and insulin resistance." (PMID 40510487, 2025). "Liver-specific deletion of BMAL1 disrupts glucose and lipid metabolism, leading to insulin resistance and hepatic steatosis." (PMID 40510487, 2025). "Mice with skeletal muscle Bmal1 overexpression developed insulin resistance under sleep deprivation, indicating impaired metabolic adaptability to homeostatic stress." (PMID 41139729, 2025). "Jacobi and his colleagues also observed insulin resistance when they studied changes in mitochondrial dynamics by knocking out the BMAL1 gene." (PMID 37215098, 2023). "Glucosamine increases insulin resistance, which is ameliorated by capsaicin in a Bmal1-dependent manner." (PMID 36838862, 2023). "A recent study showed that Bmal1 deletion also protects mice from insulin resistance induced by circadian disruption." (PMID 33363534, 2020). "In this study, we demonstrated that DHEA-induced PCOS-like rats exhibited insulin resistance as well as arrhythmic expression of circadian clock genes in the liver and adipose, particularly showing decreased BMAL1 expression." (PMID 32334629, 2020). "The disrupted rhythmic expression of circadian clock genes, specifically decreased BMAL1 expression, mediated the contribution of hyperandrogenism to insulin resistance in PCOS." (PMID 32334629, 2020). "BMAL1 knockdown induces insulin resistance, as indicated by markedly impaired insulin-stimulated phosphorylation of insulin receptor and AKT pathway." (PMID 32334629, 2020). "The studies have discovered that EGCG and tea polyphenols reduce insulin resistance in a Bmal1-dependent way and by activating AMPK signaling pathways." (PMID 33381029, 2020). "After further adjusting for multiple testing, the association between DNA methylation at only 1 CpG site in the BMAL1 gene remained to be statistically significant in relation to insulin resistance at q < 0.05." (PMID 31031806, 2019). "Additionally, Bmal1 knockout mice display higher rates of insulin resistance compared to wild-type mice, and transgenic Bmal1 overexpression in knockout mice ameliorates the elevated insulin resistance." (PMID 39165284, 2024). "Moreover, relative to wild-type mice, Clock or Bmal1 knockdown mice exhibit insulin resistance in muscle cells." (PMID 39165284, 2024). "Consequently, liver-specific Bmal1 knockout mice accumulate oxidative damage and develop hepatic insulin resistance." (PMID 36837757, 2023).
Insulin resistance (continued). "Another natural product, LBP‐4a prepared from Lycium barbarum, can improve hyperglycemia and insulin resistance by regulating biological rhythms, which are related to the increased expression of Bmal1 in pancreatic islet cells to improve impaired pancreatic islets." (PMID 36056774, 2022). "Thus, our study uncovered the potentially novel role of BMAL1 in the contribution of hyperandrogenism to insulin resistance in PCOS." (PMID 32334629, 2020). "Secondly, since we proposed and confirmed the role of BMAL1 in the contribution of hyperandrogenism to insulin resistance in PCOS, it might be a novel potential therapeutic target for PCOS patients." (PMID 32334629, 2020). "As such, BMAL1 may be an important mediator of the effects of NS work on peripheral clock misalignment and insulin resistance." (PMID 32899117, 2020). "Based on the arrhythmic Nampt and Sirt1 mRNA expressions in the liver and adipose of PCOS-like rats, we speculated that NAMPT and SIRT1 might be the bridge linking BMAL1 and insulin resistance in PCOS patients." (PMID 32334629, 2020). "Hence the change in BMAL1 expression plays a potential role in hyperandrogenism-induced insulin resistance in PCOS." (PMID 32334629, 2020). "A study highlighted the importance of the liver clock genes BMAL1, PER1, and PER2 in PCOS; when rats were exposed to constant darkness, their liver clock genes became desynchronized with the environment, causing a decrease in BMAL1 levels, which promoted insulin resistance." (PMID 39858445, 2025). "Recently, by using chromatin immunoprecipitation sequencing, researchers have found that CLOCK and BMAL1 could bind to inner-mitochondrial genes related to insulin sensitivity, suggesting that the relationship between circadian rhythm and insulin resistance may be related to mitochondrial dynamics." (PMID 37215098, 2023). "Overall, our findings support the role of Berberine in mitigating glucose metabolism, insulin resistance, lipid dysfunction, and liver inflammation in the progression of MAFLD by Clock genes Bmal1/Clock-mediated oxidative stress and circadian misalignment." (PMID 36838862, 2023). "Hyperandrogenism resulted in the negative regulation of BMAL1-induced expression of the NAMPT/NAD+/SIRT1 pathway, which further suppressed GLUT4, leading to insulin resistance in the liver and adipose tissues of rats." (PMID 32334629, 2020). "At the level of q < 0.05, gene-based analysis detected significant associations of DNA methylation in four circadian genes (CLOCK, BMAL1, PER1, and PER2) with insulin resistance, fasting glucose, or HbA1c." (PMID 31031806, 2019). "Furthermore, the negatively regulated gene BMAL1, REV-ERB, plays a role in the regulation of metabolic processes, including insulin resistance and lipid metabolism problems, and exerts an inhibitory influence on granulosa cell apoptosis in PCOS." (PMID 40475989, 2025). "DHEA-induced PCOS-like rats exhibited insulin resistance and arrhythmic expression of circadian clock genes in the liver and adipose tissues, particularly showing decreased brain and muscle ARNT-like protein 1 (BMAL1) expression." (PMID 32334629, 2020). "Meanwhile, hyperandrogenism led to the negative regulation of BMAL1-induced expression of NAMPT/NAD+/SIRT1 pathway, further inhibiting downstream GLUT4 and contributing to insulin resistance in mature adipose cells, which was consistent with our previous results in HepG2 cells." (PMID 32334629, 2020). "A lack of liver Bmal1 leads to severe insulin resistance and hepatic steatosis after feeding on a chronic high-fat diet." (PMID 33381029, 2020). "Interestingly, SIRT1 regulates the key components of the circadian clock, CLOCK and BMAL1, and when circadian misalignment is induced in mice, reduced hepatic BMAL1 and SIRT1 levels and insulin resistance ensue." (PMID 29264533, 2017).
Insulin resistance (continued). "Crucially, nobiletin combats insulin resistance, protects pancreatic β-cell function, enhances insulin secretion, and modulates key signaling pathways (including AMPK, PI3K/AKT, PPARs, NF-κB, and circadian regulators like Bmal1/RORs) to improve glucose and lipid homeostasis." (PMID 41155643, 2025). "The result suggested that the protein levels of Clock and Bmal1 were decreased in MAFLD mice, which was negatively correlated with elevated reactive oxygen species (ROS) accumulation, the H2O2 level, liver inflammation, metabolic dysfunction, and insulin resistance." (PMID 36838862, 2023). "Decreased BMAL1 expression in the liver and adipose played a potentially novel role in the contribution of hyperandrogenism to insulin resistance, which might be a possible mechanism accounting for the pathogenesis of PCOS." (PMID 32334629, 2020). "Whether HF-induced reprogramming is due to specific nutrients in the diet vs. the resulting insulin resistance has not been directly demonstrated, and the extent to which other insulin-resistant tissues are affected is not clear from the standpoint of BMAL1 function." (PMID 29795456, 2019).
Hypertension (34 papers, 2010 to 2025). The presence of chronic increased pressure in the systemic arterial system. "In line with a previous study of healthcare workers that identified the TT genotype of BMAL1 rs11022775 as protective against hypertension (OR = 0.426), our study found a significant associations of the BMAL1 SNP rs11022780 with PE." (PMID 41226832, 2025). "Genes like Bmal1, Clock, Period, and Cryptochrome manage blood pressure, and their disturbances cause oxidative stress and inflammation, leading to hypertension." (PMID 39763690, 2024). "SNPs in the neural PAS domain protein 2 structure, a CLOCK-like protein that binds to BMAL1, are also linked to metabolic syndrome risk factors like high blood pressure." (PMID 39062777, 2024). "A genetic association study designed to test the relevance of 19 polymorphisms of BMAL1 in 1304 individuals showed that two BMAL1 haplotypes were associated with type 2 diabetes and hypertension." (PMID 37298261, 2023). "Bmal1 SNPs are associated with high blood pressure in addition to T2DM, hyperglycemia, and gestational diabetes." (PMID 37441501, 2023). "The GG genotype in BMAL1 rs7950226 SNP was associated with insulin resistance in patients with essential hypertension in a Chinese population." (PMID 37761843, 2023). "Analysis of single‐nucleotide polymorphisms (SNPs) has elucidated that BMAL1 is associated with susceptibility to hypertension." (PMID 36056774, 2022). "SNPs in Bmal1 have also been associated with hypertension, hyperglycemia, T2DM and gestational diabetes." (PMID 36034454, 2022). "Further, angiotensin II is elevated in Ahr-null mice, and the AHR-associated gene Bmal1 lies within a hypertension-susceptibility locus." (PMID 21760882, 2011). "Woon and colleagues (2007) identified polymorphisms in the promoter region of Bmal1 (Brain and muscle Arnt-like protein-1) that were within the same congenic interval associated with hypertension in the spontaneously hypertensive rat (SHR)." (PMID 22076133, 2011). "Other studies have revealed associations between: polymorphisms in BMAL1 with hypertension and type 2 diabetes, hypertension and NPAS2 (CLOCK gene analogous), and glucose and PER2." (PMID 20712885, 2010). "Hypertension in db/db mice is associated with attenuated Bmal1 oscillations in the vasculature." (PMID 36056774, 2022). "Based on clinical SNP data on Bmal1, strong associations have been found between Bmal1 SNPs that confer reduced transcriptional efficiency and increased susceptibility to type 2 diabetes and hypertension." (PMID 35626652, 2022). "Moreover, two different BMAL1 SNP haplotypes have been shown to be associated with type 2 diabetes and hypertension in patients, suggesting an important contribution of BMAL1 variants to the pathogenesis of these disease mechanisms." (PMID 33519516, 2020). "Two BMAL1 haplotypes are associated with type 2 diabetes and hypertension." (PMID 25414671, 2014). "Genetic variation in BMAL1 is associated with the development of hypertension in man." (PMID 25414671, 2014). "BMAL1 dysfunction is associated with susceptibility to hypertension and type 2 diabetes." (PMID 25414671, 2014). "Second, SNP analysis revealed that BMAL1 is associated with type II diabetes and hypertension." (PMID 21966465, 2011). "Furthermore, the same group reported a significant genetic association of Bmal1 polymorphisms and hypertension and type II diabetes in humans." (PMID 22076133, 2011). "In addition, analysis of SNPs has revealed that BMAL1 is associated with susceptibility to hypertension and type II diabetes." (PMID 21966465, 2011). "Intriguingly, BMAL1 and CLOCK gene polymorphisms have been associated with hypertension in a study of healthcare workers, supporting their potential role in PE pathologies." (PMID 41226832, 2025).
Hypertension (continued). "Others studies investigated the relationship between aryl hydrocarbon receptor nuclear translocators such as Arntl, also known as BMAL1, rs6486121, and clock circadian regulator (Clock) T3111C with hypertension." (PMID 36672629, 2023). "Polymorphisms of the BMAL1 gene, which is the mouse equivalent of the human ARNTL gene, are connected with hypertension and T2DM, just as in this study where we found an association of rs3789327 and rs12363415 with T2DM in MI patients." (PMID 32050674, 2020). "Hypertension, T2DM, hyperglycemia, and gestational diabetes are linked to Bmal1 SNPs." (PMID 39062777, 2024). "The clock gene Bmal1 is reported to be highly correlated with the etiology of hypertension." (PMID 36056774, 2022). "In contrast, gene expression profiling of Spontaneously Hypertensive (SHR) rats, a genetic model of hypertension, demonstrated decreased expression of Bmal1 and Npas2, while Per1, Per2, Per3, Cry1, Cry2, Bhlhe41 and Csnk1D were all upregulated compared to naïve WKY controls." (PMID 33127986, 2020). "Few candidate gene studies reported associations of single nucleotide polymorphisms (SNPs) in CLOCK, ARNTL (encoding BMAL1), and PER2 with risk factors for the metabolic syndrome and type-2 diabetes, such as abdominal obesity, hypertension, fatty liver, and an atherogenic lipid profile." (PMID 26726810, 2016). "In a genetic animal model of hypertension, the spontaneously hypertensive (SHR) rats, the expression of Bmal1 was decreased." (PMID 36056774, 2022). "Beyond placental and oxidative stress mechanisms, BMAL1 dysfunction may also impair vascular function by negatively influencing VEGF signaling and promoting endothelial inflammation and dysfunction, thereby contributing to the systemic vascular abnormalities and hypertension in eoPE." (PMID 41226832, 2025).
type 2 diabetes (32 papers, 2010 to 2026). "Specifically, in the present study, we established causality by inhibiting the action of the CLOCK/BMAL1 complex, having observed that leukocyte–endothelial interactions were enhanced in a similar way to that seen in type 2 diabetes participants." (PMID 38981930, 2024). "The brain and muscle Arnt-like protein-1 (BMAL1) gene is an important circadian clock gene and previous studies have found that certain polymorphisms are associated with type 2 diabetes in adults." (PMID 36732647, 2023). "Loss of islet clock function in islet-specific Bmal1 KO mouse models, either induced during development or in the adult age, resulted in the early onset of type 2 diabetes (T2D) in these mice." (PMID 28439257, 2017). "The BMAL1 locus was associated with type 2 diabetes in our Punjabi populations, albeit with borderline significance." (PMID 22485135, 2012). "Notably, disruptions to the internal oscillation period of the Bmal1 gene in pancreatic islet tissue were associated with increased risk of type 2 diabetes (T2D) and obesity." (PMID 39667926, 2024). "Loss of Bmal1 is associated with type 2 diabetes due to pancreatic β-cell failure." (PMID 32964049, 2020). "The rs7602358G allele near PER2 was negatively associated with type 2 diabetes in our Punjabi cohorts (combined odds ratio [OR] = 0.75 [0.66–0.86], p = 3.18×10−5), while the BMAL1 rs11022775T allele was associated with an increased risk of the disease (combined OR = 1.22 [1.07–1.39], p = 0.003)." (PMID 22485135, 2012). "BMAL1 gene expression levels were higher in leukocytes from the participants with type 2 diabetes group than in those from the healthy participants (p<0.05)." (PMID 38981930, 2024). "In contrast, protein levels of the phosphorylated active form of BMAL1 (p-BMAL1) were lower in the type 2 diabetes group (p<0.05)." (PMID 38981930, 2024). "Conversely, BMAL1 is severely depleted in islets from patients with type 2 diabetes (T2D) and disrupted by IL-1β exposure of islets in vitro." (PMID 32650582, 2020). "However, the transcript levels of these genes were unchanged in the type 2 diabetes group vs healthy participants, except for BMAL1, whose levels were higher in the former group." (PMID 38981930, 2024). "Interestingly, inhibition of CLOCK/BMAL1 activity in leukocytes using the CLOCK inhibitor CLK8 mimicked the effects of type 2 diabetes on leukocyte–endothelial interactions." (PMID 38981930, 2024). "Additionally, in patients with type 2 diabetes, those with the poorest sleep quality showed a dampened mRNA expression of clock genes such as BMAL1 and PER1." (PMID 32823749, 2020). "In a human study, leucocytes sampled from subjects with type 2 diabetes expressed significantly lower transcript levels of BMAL1, PER1, and PER3 compared with leucocytes from normal controls; moreover, transcript expression was inversely correlated with HbA1c levels." (PMID 28352282, 2017). "Disruption of the clock components Clock and Bmal1 leads to hypoinsulinemia and type 2 diabetes." (PMID 25414671, 2014). "Our data demonstrate a dysregulation of the molecular clock system in PBMCs from participants with type 2 diabetes, manifested by a decrease in CLOCK, CRY1, p-BMAL1 and PER2 protein levels and an increase in BMAL1 and NR1D1 mRNA levels." (PMID 38981930, 2024). "On the other hand, mechanisms that impair the circadian clock genes, such as circadian locomotor output cycles kaput (CLOCK), brain and muscle Arnt-like protein 1 (BMAL1), and period genes (PER1, PER2, and PER3), contribute to defective beta-cell function and development of type 2 diabetes." (PMID 28352282, 2017). "Impairment of the circadian clock genes such as CLOCK, BMAL1, cryptochrome (CRY1 and CRY2), and period (PER1, PER2, and PER3) contributes to the decrease in glucose tolerance, defective β-cell function, and the development of type 2 diabetes." (PMID 28352282, 2017).
type 2 diabetes (continued). "Participants with type 2 diabetes showed increased BMAL1 and NR1D1 mRNA levels and decreased protein levels of circadian locomotor output cycles kaput (CLOCK), cryptochrome 1 (CRY1), phosphorylated basic helix-loop-helix ARNT like 1 (p-BMAL1) and period circadian protein homologue 2 (PER2)." (PMID 38981930, 2024).